SLC1A1 (solute carrier family 1 member 1)
Diseases named in the same sentence as SLC1A1 in open-access papers (continued):
Sharing a sentence is not in itself a finding about the gene and the disease.
breast carcinoma (6 papers, 2013 to 2024). "SLC1A1 is expressed in the luminal subtype of breast cancer, while SLC1A5 is expressed in the HER2-positive subtype." (PMID 39852119, 2024). "Here, we would like to suggest that the overall increased expression of SLC1A1 in TNBC and luminal breast cancer may be associated with the heterogeneity of the TNBC subgroup." (PMID 39852119, 2024). "The transporters SLC1A1, SLC7A1, and SLC7A11 are highly expressed in luminal subtypes of breast cancer and TNBC." (PMID 39852119, 2024). "Apparently, the overall increased expression of SLC1A1 in luminal and TNBC is characteristic of basal-like A breast cancer." (PMID 39852119, 2024). "Hypoxia did not induce SLC1A1 and SLC1A3 mRNA in two breast cancer cell lines." (PMID 25326682, 2014).
multiple sclerosis (5 papers, 2016 to 2025). A progressive autoimmune disorder affecting the central nervous system resulting in demyelination. "EAAC1 (SLC1A1) has reduced expression in multiple sclerosis (MS), impairing glutamate clearance and exacerbating neuroinflammation and excitotoxicity." (PMID 41425581, 2025).
depression (4 papers, 2020 to 2024). "Additional miRNAs targeting glutamate transmission is miR-101b, downregulated in the prefrontal cortex of a genetic animal model of depression, which inhibit the glutamate transporter SLC1A1 (also known as EAAC1 or EAAT3), upregulated in depression." (PMID 34829888, 2021).
lung carcinoma (4 papers, 2015 to 2025). "We selected 6 loci displaying significant differential cirDNA modification in the microarray analysis (Rab3a, Atp6v0c, B4galnt1, Slc1a1, Ttl and Krt15) and whose corresponding genes have been reported as associated to lung cancer phenotypes." (PMID 25415227, 2015).
neuroblastoma (4 papers, 2017 to 2025). Neuroblastoma (NB) is the most common solid, extracranial childhood tumor. "In vitro overexpression of SLC1A1 in human neuroblastoma SK-N-SH cells is correlated with decreased cytokine expression after an oxidative inflammatory challenge." (PMID 34944156, 2021). "This latter finding was further supported by SLC1A1 knockdown and overexpression studies in differentiated human neuroblastoma cells, which led to decreased or increased cytokine expression, respectively." (PMID 28886095, 2017). "We next examined how overexpression or knockdown of SLC1A1 might affect the response of differentiated human neuroblastoma SK-N-SH cells to oxidative stress or pro-inflammatory stimuli using rotenone or LPS treatment." (PMID 28886095, 2017).
psychosis (4 papers, 2015 to 2024). "None of the glutamatergic and serotonergic genetic variants were found to moderate the effect of psychosis on obsession and compulsion (SLC6A4, SLC1A1 and HTR2C) survived the multiple comparisons correction." (PMID 38652060, 2024).
colorectal cancer (3 papers, 2020 to 2021). A primary or metastatic malignant neoplasm that affects the colon or rectum. "In brief, EAAT3 (SLC1A1) overexpression was detected in brain and prostate cancer cells, being associated with increased chemoresistance in colorectal cancer models." (PMID 32714858, 2020). "In colorectal cancer, the expression of SLC1A1 is significantly and positively correlated with the level of CD8+ T cells and dendritic cell infiltration." (PMID 34349753, 2021). "Three novel genes, CNTN3, SLC1A1, and SLC16A9 were shown to have diagnostic value with respect to the occurrence of colorectal cancer and should be verified in future studies." (PMID 32566650, 2020).
dicarboxylic aminoaciduria (3 papers, 2019 to 2023). "Dicarboxylic aminoaciduria is a rare autosomal recessive disorder due to a mutation of SLC1A1 that encodes EAAT3 found in the intestine, kidney, and brain." (PMID 37764806, 2023). "Lastly, two cases of human dicarboxylic aminoaciduria were caused by mutations in SLC1A1: a three base pair deletion (c.1184–1186delTCA) and a base pair exchange causing the R445W mutation in EAAT3." (PMID 33587237, 2022).
hepatoma (3 papers, 2014 to 2024). "For instance, hypoxia-inducible factor (HIF)-1 and HIF-2 proteins increase SLC1A1/3 gene expression in hepatocellular carcinoma (HCC) and clear cell renal carcinoma cells (ccRCC) under hypoxic conditions to increase proliferation." (PMID 38705513, 2024). "We next analyzed the prognostic implication of the HIF regulated genes involved in glutamate signaling in hepatocellular carcinoma (SLC1A1, SLC1A3, GRIA2, GRIA3 and FYN) using PROGgene to analyze the GSE 10141 mRNA expression data set from 80 surgically resected hepatomas." (PMID 25326682, 2014).
clear cell renal cell carcinoma (2 papers, 2014 to 2019). "This study aimed to comparatively analyze the expression levels of the SLC1A1 gene in renal specimens from tumors and adjacent healthy kidney tissues of patients with clear cell renal cell carcinoma (ccRCC)." (PMID 30862152, 2019).
lung adenocarcinoma (2 papers, 2021 to 2025). A carcinoma that arises from the lung and is characterized by the presence of malignant glandular epithelial cells. "In human lung adenocarcinoma, low SLC1A1 expression is correlated with tumor stage, histological subtype, nodal metastasis status, and poor overall survival." (PMID 40005897, 2025).
post-traumatic stress disorder (2 papers, 2017 to 2020). An anxiety disorder precipitated by an experience of intense fear or horror while exposed to a traumatic (especially life-threatening) event. "Some SNP variants in SLC1A1 are also reported to significantly increase the likelihood of post-traumatic stress disorder in combat-exposed veterans." (PMID 32507125, 2020).
prostate carcinoma (2 papers, 2020 to 2023). A carcinoma that arises from epithelial cells of the prostate gland. "Glutamate and aspartate transporting SLC1A1 is expressed in prostate cancer and has been studied to be regulated by testosterone." (PMID 36809527, 2023). "Our results link low expression of SLC1A1 to poor progression-free survival thus emphasizing the significance of glutamate signaling also in prostate cancer." (PMID 36809527, 2023).
renal cell carcinoma (2 papers, 2016 to 2026). "Renal cell carcinomas (RCCs) depend on the trimeric sodium-coupled aspartate and glutamate transporter, SLC1A1/EAAT3; however, pharmacologically targeting SLC1A1 is challenging." (PMID 42020573, 2026).
Stroke (2 papers, 2012 to 2019). Sudden impairment of blood flow to a part of the brain due to occlusion or rupture of an artery to the brain. "For stroke, Apcdd1, Atp2b2, Axin2, ITIH-5 and Slc1a1 are specifically expressed in brain vasculome." (PMID 23285140, 2012).
adenomyosis (1 paper, 2020). The growth of endometrial tissue inside the muscular wall of the uterine corpus. "SPP1, LIF, TCN1 and CLDN4 were common to adenomyosis and healthy groups of genes, while ANXA2, EDNR8, MMP26, DEPP1, ABCC3, CDA and SLC1A1 were common to endometriosis and healthy groups." (PMID 32933042, 2020).
Aminoaciduria (1 paper, 2025). An increased concentration of an amino acid in the urine. "The review highlighted 9 genes associated with aminoacidurias, including SLC3A1 (rBAT), SLC7A9 (bo,+AT), SLC6A19 (BoAT1), SLC7A7 (y+LAT1), SLC7A6 (y+LAT2), SLC36A2 (PAT-2), SLC6A20 (SIT-1), SLC6A18 (BoAT3), and SLC1A1 (EAAT3)." (PMID 41142409, 2025).
anemia (1 paper, 2019). A reduction in the number of red blood cells, the amount of hemoglobin, and/or the volume of packed red blood cells. "Most studies in the literature support our findings with respect to the relationship of SLC1A1 expression in ccRCC with anemia." (PMID 30862152, 2019).
chronic tic disorder (1 paper, 2018). A neurological disorder presenting in childhood that is characterized by either motor or phonic tics, but not both, that occur daily or nearly daily for at least a year and are not attributed to an identifiable cause. "We only found a nominally significant association for the glutamate transporter gene SLC1A1 with chronic tic disorder (P value = 0.02)." (PMID 28555406, 2018).
fibrosis (1 paper, 2025). the formation of excess fibrous connective tissue in an organ or tissue in a reparative or reactive process. "The expression of SLC1A1 decreases in cases of renal interstitial fibrosis, with a more pronounced reduction as fibrosis worsens." (PMID 41480525, 2025). "This research sought to examine the role of solute carrier family 1 member 1 (SLC1A1) in renal interstitial fibrosis (RIF), exploring its relationship with fibrosis extent and its influence on amino acids absorption and ion levels." (PMID 41480525, 2025).
gastric cancer (1 paper, 2025). A primary or metastatic malignant neoplasm involving the stomach. "This interplay between ERBB3 and SLC1A1 appears to involve HIF1α, which can be upregulated by heregulin and has been implicated in ferroptosis resistance in gastric cancer." (PMID 40846695, 2025).
Hypoglycemia (1 paper, 2010). A decreased concentration of glucose in the blood. "Dicarboxylicamino aciduria exhibits impaired renal glutamate and aspartate reabsorption and hypoglycemia resulting from a deficient glutamate transporter (SLC1A1), all symptoms predicted by the model." (PMID 20957118, 2010).
kidney tumor (1 paper, 2019). "The expression of the SLC1A1 gene in kidney tumor tissues increased approximately 3 times compared with normal kidney tissues, which was statistically significant." (PMID 30862152, 2019). "The expression of the SLC1A1 gene in kidney tumor tissues increased approximately 3 times compared with normal kidney tissues." (PMID 30862152, 2019).
liver cancer (1 paper, 2025). An epithelial or non-epithelial malignant neoplasm that arises from the liver. "In human liver cancer, SLC1A1 is downregulated compared with that in the normal liver." (PMID 40005897, 2025).
lymphoma (1 paper, 2023). A malignant (clonal) proliferation of B- lymphocytes or T- lymphocytes which involves the lymph nodes, bone marrow and/or extranodal sites. "SLC1A1 overexpression in lymphoma not only enhanced tumor growth, but also promoted competition for Gln between lymphoma cells and CD8+ T cells." (PMID 37032776, 2023).
melanoma (1 paper, 2022). A malignant, usually aggressive tumor composed of atypical, neoplastic melanocytes. "Another inhibitor of SLC1A1 is the benzyl serine, which has antiproliferative properties in melanoma cell lines." (PMID 35406721, 2022).
metastatic tumors (1 paper, 2021). "Furthermore, increased SLC1A1 in human OSA microarray datasets has been associated with metastatic tumors and a worse prognostic effect." (PMID 34414229, 2021).
osteoarthritis (1 paper, 2021). A noninflammatory degenerative joint disease occurring chiefly in older persons, characterized by degeneration of the articular cartilage, hypertrophy of bone at the margins and changes in the synovial membrane. "The SLC1A1 agonist and neuropathic pain inhibitor pregabalin is commonly prescribed in osteoarthritis." (PMID 34450027, 2021).
ovarian carcinoma (1 paper, 2015). A malignant neoplasm originating from the surface ovarian epithelium. "Although this is, to our knowledge, the first study to demonstrate SLC1A1 protein and activity changes in drug-resistant cancer cells, altered SLC1A1 mRNA expression was also reported in ovarian cancer cells and in the NCI-60 cancer cell line panel, suggesting a more widespread relevance than CRC." (PMID 25981639, 2015).
polycystic kidney disease (1 paper, 2021). A usually autosomal dominant and less frequently autosomal recessive genetic disorder characterized by the presence of numerous cysts in the kidneys leading to end-stage renal failure. "In our analysis, we identify SLC1A1 as being over-expressed in Polycystic Kidney Disease." (PMID 33826640, 2021).
renal fibrosis (1 paper, 2025). A final common manifestation of a wide variety of chronic kidney diseases characterized by glomerulosclerosis and tubulointerstitial fibrosis. "Findings from cell culture experiments demonstrate a decline in SLC1A1 during fibrosis, with its expression inversely related to the severity of renal fibrosis." (PMID 41480525, 2025). "To further investigate the alterations of SLC1A1 in the progression of renal fibrosis and its impact on amino acid and ion concentrations, we conducted the following experiments." (PMID 41480525, 2025).
tuberculous meningitis (1 paper, 2025). "Finally, SLC1A1 and SLIT3 variants were associated with susceptibility to tuberculous meningitis and subsequent survival, respectively, in a Vietnamese cohort." (PMID 40402573, 2025).
viral infection (1 paper, 2025). "IFN-stimulated genes (ISGs), including CRP, IFIT1, LRG1, SLC1A1, and CDKN1A, were upregulated during HBoV1 infection, suggesting that viral infection elicited an antiviral response from the host cell." (PMID 39846742, 2025).
tumor (15 papers, 2014 to 2025). "SLC1A1 promotes tumor development in lung cancer and NK T-cell lymphoma by regulating glutamine metabolism and R-2-HG levels." (PMID 41425581, 2025). "Targeting SLC1A1 can inhibit glutamine metabolism, reduce R-2-HG accumulation, and thereby suppress tumor cell proliferation while enhancing the efficacy of chemotherapy." (PMID 41425581, 2025). "Solute carrier family 1 member 1 (SLC1A1), a soluble ectopic transporter on tumor cell membrane increased cellular glutamine uptake." (PMID 38396050, 2024). "Among AR-association gained genes, new candidate genes that strongly associated with aggressive tumor traits were sprouty related EVH1 domain containing 3 (SPRED3), transmembrane serine protease 11F (TMPRSS11F) and solute carrier family 1 member 1 (SLC1A1)." (PMID 36809527, 2023). "The expression of the SLC1A1 gene in tumor tissues increased approximately 3 times compared with normal kidney tissues (P < 0.05)." (PMID 30862152, 2019). "The change in the expression levels of the SLC1A1 gene between the tumor and normal kidney tissues was statistically significant (P < 0.05)." (PMID 30862152, 2019). "The expression levels of the SLC1A1 gene in tumor tissues and the healthy kidney tissues surrounding the tumors of 19 ccRCC patients were compared and possible associations between the clinical parameters of the patients and gene expression levels were investigated." (PMID 30862152, 2019). "Tumor samples of patients with ccRCC were compared with healthy kidney tissues around the tumor of the same patient with respect to the expression levels of the SLC1A1 gene." (PMID 30862152, 2019). "Tumor samples of patients with ccRCC were compared with healthy kidney tissues around the tumor of the same patient with respect to the expression level of the SLC1A1 gene." (PMID 30862152, 2019). "The expression levels of the SLC1A1 and GAPDH genes were measured in tumor and formalin-fixed paraffin-embedded (FFPE) tissue specimens from the adjacent healthy kidney of each subject." (PMID 30862152, 2019). "This cell line also mostly mimicked downregulated small molecule transporters seen in tumours, e.g. NPC1L1, SLC25A15/20, SLC2A2, SLC1A1 and SLC7A2." (PMID 30176945, 2018). "Similarly, a separate study presented a cuproptosis-related gene signature (involving TNFRSF18, SLC1A1, among others) to assess patient outcomes and the tumor immune environment, although it lacked clinical sample validation." (PMID 38326441, 2024).
cancer (14 papers, 2014 to 2025). A tumor composed of atypical neoplastic, often pleomorphic cells that invade other tissues. "SLC1A1 is often upregulated in cancers compared to normal tissues but also downregulated in some cases and in metastatic PCa compared to primary PCa." (PMID 36809527, 2023). "Analyzing gene expression data from 42 ccRCCs in the International Cancer Genome Consortium revealed that SLC1A1, GRIA3 and FYN mRNA abundance was each significantly correlated with the expression of six known HIF target genes." (PMID 25326682, 2014). "However, few studies have investigated the relationship between SLC1A1 expression and cancer development." (PMID 40005897, 2025). "There have been few studies investigating the relationship between SLC1A1 expression and cancer." (PMID 32566650, 2020). "In this study, we further observed the downregulation of NRF2 target genes, namely ABCG2, GCLM, and SLC1A1, which are involved in ferroptosis regulation, only in HSC2 cancer cells." (PMID 39857335, 2024). "However, the role of SLC1A1 in the development of cancer remains unclear." (PMID 36528667, 2022).
neurological disorders (5 papers, 2011 to 2025). "The SLC1 subfamily, specifically SLC1A3 (EAAT1), SLC1A2 (EAAT2), and SLC1A1 (EAAT3), are excitatory amino acid transporters that regulate glutamate concentrations in the synaptic cleft, making them important targets for neurological disorder therapeutics." (PMID 40308755, 2025).
genetic diseases (1 paper, 2022). "The linkage of human genetic diseases to genes encoding EAAT1 (SLC1A3), EAAT2 (SLC1A2) and EAAT3 (SLC1A1) revealed additional roles of EAATs in cell and organ physiology." (PMID 33587237, 2022).
intestinal diseases (1 paper, 2020). "At present, there is still a lack of research into SLC1A1, SLC16A9, and CNTN3 related to intestinal diseases." (PMID 32566650, 2020).
kidney diseases (1 paper, 2025). "Studies have demonstrated that the protein encoded by the SLC1A1 gene is critical for kidney function, with its functional abnormalities linked to dicarboxylate aminouria, a rare kidney disease characterized by disorders in amino acid metabolism." (PMID 41480525, 2025). "Despite being an important amino acid transporter and a protein that regulates acid–base electrolyte balance, the role of SLC1A1 in various kidney diseases has not received adequate attention, and its mechanisms of action remain insufficiently explored." (PMID 41480525, 2025).
SLC1A1 also shares sentences with these, for which no sentence is quoted: ischemia (7 papers); normal tension glaucoma (7); glaucoma (6); Cerebral ischemia (5); neurodegenerative disease (5); Parkinson disease (5); Huntington disease (4); retinal degeneration (4); Alzheimer disease (3); autism spectrum disorder (3); ischemic stroke (3); temporal lobe epilepsy (3); transient cerebral ischemia (3); amyotrophic lateral sclerosis (2); brain injury (2); epileptic seizures (2); glioblastoma (2); peripheral nerve injury (2); Acidosis (1); anxiety disorder (1); attention deficit-hyperactivity disorder (1); central nervous system disorder (1); colorectal adenoma (1); cortical dysplasia (1); demyelinating disease (1); diabetes (1); endocrine system disorder (1); endometriosis (1); essential tremor (1); febrile seizures (1).
A further 19 diseases each share a sentence with SLC1A1 in 1 paper.